FASLG (Fas ligand)
Diseases named in the same sentence as FASLG in open-access papers (continued):
Sharing a sentence is not in itself a finding about the gene and the disease.
melanoma (94 papers, 2002 to 2025). A malignant, usually aggressive tumor composed of atypical, neoplastic melanocytes. "The mechanism of apoptosis triggered by Fas-ligand was shown in a genetically engineered melanoma mouse model resistant to checkpoint blockade in which lymphocytes in the periphery were consecutively depleted." (PMID 35805052, 2022). "In melanoma, Fas ligand (FasL)-bearing microvesicles trigger Fas-dependent apoptosis of lymphoid cells." (PMID 36704194, 2022). "BOK and CYLD were down-regulated, and CD14 and FASLG were up-regulated in melanoma samples, which were in accordance with the bioinformatics results." (PMID 35387121, 2022). "For example, FASLG can reduce the melanoma cells’ mediated apoptosis to affect SKCM patients’ prognosis." (PMID 35899194, 2022). "Fas ligand (FasL) has been reported to be highly expressed in various types of tumor cell-derived exosomes, including ovarian cancer, melanoma, prostate cancer, and oral squamous cell carcinoma." (PMID 34616851, 2021). "The plasma of melanoma patients harbor increased levels of exosomes that contain immunosuppressive proteins such as Fas ligand (FasL) and transforming growth factor beta (TGF-β), melanoma-associated antigens (MAAs), and oncoproteins, including Myc." (PMID 34575889, 2021). "Fas ligand (FasL) is present in EVs of melanoma cells, prostate cancer cells and in epithelial ovarian cancer cells." (PMID 31281356, 2019). "For instance, EVs expressing Fas ligand increase T-cell apoptosis in human melanoma and colorectal cancer cells." (PMID 29362448, 2018). "For example, Fas ligand (FasL)-containing microvesicles from melanoma cells triggered apoptosis of Jurkat and other lymphoid cells." (PMID 28101591, 2017). "In opposition to the results in the previous section, endogenous IL-18 from melanoma cells was also found to inhibit NK cell-mediated killing of melanoma cells by upregulating Fas ligand expression." (PMID 24795727, 2014). "Previous study showed that Geraniin-induced apoptosis occurs by caspase-3-mediated FAK cleavage through upregulation of Fas ligand expression in human melanoma cells." (PMID 25945102, 2013). "Here we use a model of tumour rejection involving a melanoma cell line expressing Fas ligand (B16FasL) to study the effect of Treg on both innate and adaptive immune responses." (PMID 17294404, 2007). "Fas ligand was positively correlated with the ζ and ɛ chains and p56lck in melanoma TIL, and only with the ɛ chain and p56lck in colorectal carcinoma TIL." (PMID 12610520, 2003). "Conversely, Tex-C1 cells may impact, on the other hand, may influence melanoma prognosis by downregulating the melanogenesis pathway through upregulated expression of increased FASLG expression." (PMID 38460046, 2024). "Although FASLG is abundantly expressed in melanoma patients, its involvement in malignant cells apoptosis remains unclear." (PMID 38460046, 2024). "By using qRT-PCR, we also found that FASLG was highly expressed in melanoma samples." (PMID 35387121, 2022). "Thus, FASLG is found to be highly expressed in several tumors, including cervical cancer, melanoma and bladder cancer." (PMID 35387121, 2022). "In addition, melanoma cells pre-treated with ROCK inhibitors have shown suppressed tumor growth through the increase in the Fas ligand (FasL) and the corresponding infiltration of CD8+ T lymphocytes." (PMID 34884721, 2021). "Finally, it has been reported that PMN-MDSCs expressing high levels of Fas-ligand trigger apoptosis of tumor-infiltrating lymphocytes through the Fas/Fas-ligand axis, which results in immunotherapy resistance in the autochthonous TiRP melanoma model." (PMID 35003065, 2021). "It was also described that Fas signaling promote lung cancer growth by recruiting myeloid-derived suppressor cells (MDSCs) in vivo and the bioactive Fas ligand (FasL) released by activated T cells in exosomes promotes melanoma and lung cancer cell metastasis through Fas signaling." (PMID 26056083, 2015).
melanoma (continued). "To this end we used a Fas ligand (FasL)-expressing melanoma cell line in a mouse model." (PMID 17294404, 2007). "The expression of cell surface Fas increases the visibility of the melanoma cells to cells of the immune system, particularly to cells expressing cell surface Fas ligand (FasL), because these cells could potentially induce apoptosis." (PMID 16545119, 2006). "Genes like FASLG, HRK and SNCA, which were observed to be downregulated, also play role in prevention of mitochondrial damage and apoptosis inhibition in melanoma/medulloblastoma cell lines." (PMID 36845715, 2023). "CYTH4, DENND1C, AOAH, TBC1D10C, EPSTI1, GIMAP7, and FASL (FAS ligand) were novel predictors of ICB therapy and displayed high level of correlations with multiple immune checkpoints in melanoma and across 30 human cancers." (PMID 36588164, 2023). "Co-culture with melanoma MCTS, resulted in defective TAA recognition by CTL as compared to 2D as witnessed by decreased IFN-γ production and decreased Fas Ligand, perforin and granzyme B gene expression." (PMID 17342088, 2007). "5-aza-2′-deoxycytidine (5-Aza) induced melanoma cell apoptosis by upregulating tumor necrosis factor (TNF)-α, Fas ligand (FasL), and TNF-related apoptosis-inducing ligand (TRAIL), demonstrating anti-melanoma effects with minimal impact on normal human melanocytes in vitro." (PMID 40497999, 2025). "According to the melanoma SCRS data, all mir-149 targets identified were expressed in lymphocytes, some of which were exclusively expressed in this cell type and include CD96, CD48, SLAMF7, FASLG, NUGGC and NLRC5." (PMID 32024530, 2020). "Interestingly, human melanoma cells silenced for FAP-1 show increased surface FAS expression and respond to recombinant FAS ligand (FasL) treatment by the induction of apoptosis." (PMID 33003469, 2020). "To elucidate the cellular mechanism, we used a Fas-ligand (Fas-L) specific ribozyme (Fas-Lribozyme) to suppress the expression of Fas-L but not Fas or TNF-α in B16F10 melanoma cells." (PMID 12177809, 2002). "Additionally, flow cytometric analysis showed no increase in surface expression of two important pathways in NK-mediated apoptosis induction, Fas ligand (FasL) and TNF-related apoptosis-inducing ligand (TRAIL), in CD276-CAR NK-92 cells upon co-incubation with melanoma cells." (PMID 33925968, 2021). "Furthermore, it has been demonstrated that EVs of tumor cells are capable of promoting immune escape by determining regulatory T cell expansion and by shedding FAS ligand (FASL), as well as by inducing CD8+T cell apoptosis and increasing expression of the MMP9 gene in melanoma cells." (PMID 33080788, 2020).
COVID-19 (81 papers, 2020 to 2025). A disease caused by infection with severe acute respiratory syndrome coronavirus 2. "A positive correlation between Fas (CD95/Apo-1) molecule expression and the plasma level of soluble Fas ligand (FasL) in patients with COVID-19 has already been associated with T-cell lymphopenia." (PMID 39859379, 2025). "Severe COVID-19 cases are also accompanied by T cell death, which is linked to plasma levels of soluble Fas Ligand (sFasL) and T cell apoptosis, with IP-10 being a characteristic feature related to disease severity." (PMID 39290698, 2024). "Th1 more than Th2 immune response–associated biomarkers are increased in patients with COVID-19, while soluble FAS ligand and soluble CD40 ligand are decreased." (PMID 33232303, 2021). "We recently suggested soluble Fas ligand (sFasL) as a prognostic marker for mortality and severity of COVID-19." (PMID 38025794, 2023). "Specifically, elevated IL-6 and IL-10 levels observed in COVID-19, can inhibit NK cytotoxicity, mediated by Granzyme-B production, Fas/FasL (Fas ligand) interaction and CD16 binding with the Fc (constant fraction) of antibodies." (PMID 35336077, 2022). "The aim was the identification of Fas/Fas Ligand (FasL) role in lung involvement and mortality of COVID-19 patients." (PMID 36119078, 2022). "We described how this triangle dysregulates immune response through Fas/Fas Ligand (FasL) in COVID-19 patients." (PMID 36119078, 2022). "We recently suggested a complex interaction of matrix metalloproteinases (MMPs), Fas ligand (FasL), and viral entry factors could be responsible for the cytokine outrage In COVID-19." (PMID 38803919, 2024). "Furthermore, we demonstrate that the levels of CD4 T-cell death and soluble Fas ligand (sFasL) correlate with weaker IgG responses in COVID-19 individuals." (PMID 36030261, 2022). "Furthermore, Fas ligand followed the opposite trend of being lower in COVID-19 patients compared with HC and lowest in severe COVID-19 patients." (PMID 34619366, 2021). "An elevated IFNA1 response displayed a strong negative correlation with IL12p40 and CX3CL1, whereas it presented a robust positive correlation with CCL11, FASLG, and IL23A, especially in severe COVID-19 patients." (PMID 36776879, 2023). "IFNA1 also presented a robust positive correlation with CCL11, FASLG, and IL23A in severe patients, and their correlation power was gradually enhanced as COVID-19 severity increased." (PMID 36776879, 2023). "To interrogate the potential role of T cell activation–related biomarkers in COVID-19 immunopathogenesis, we measured levels of IL-2, sCD25 (or sIL-2Rα), soluble CD40 ligand (sCD40LG), soluble FAS ligand (sFASLG), IL-7, and IL-3." (PMID 33232303, 2021). "Several inflammatory mediators, such as ENPP2, C5, FASLG, VWF, and CSF1, additionally presented a more robust correlation with the core inflammatory networks in the severe group, and these factors were reported as independent significant indicators of severe COVID-19 in previous studies." (PMID 36776879, 2023).
glioma (69 papers, 2001 to 2025). A benign or malignant brain and spinal cord tumor that arises from glial cells (astrocytes, oligodendrocytes, ependymal cells). "Under the influence of glioma-associated cytokines, GAMMs can upregulate immunosuppressive PD-L1, which promotes T-lymphocyte anergy as well as Fas ligand (FASL), which promotes T-lymphocyte apoptosis." (PMID 31225500, 2019). "Microglia also express and secrete Fas-ligand (FasL), which binds to Fas receptors and induces the apoptosis of invading T cells in gliomas." (PMID 38254796, 2024). "Glioma cells also express molecules that suppress the lytic action of lymphocytes, such us FAS ligand (FasL) PD-L1 and PD-L2.Specifically, the immunological synapse generated by the PD-1/PD-L1 interaction is a key point and important object of study today." (PMID 37165457, 2023). "For instance, human glioma and leukaemia CSCs express lower levels of Fas and Fas ligand (Fas-L) resulting in resistance to extrinsic receptor-mediated cell death." (PMID 31426611, 2019). "As most glioblastoma cells are resistant to apoptosis induced by Fas ligand, induction of apoptosis through this pathway in gliomas will require sensitization by other means." (PMID 22060015, 2011). "e., Fas ligand (FasL) and perforin) and inhibit the growth of glioma." (PMID 38961907, 2024). "Additionally, gliomas express Fas ligand (FasL), a protein that induces apoptosis in immune cells upon interaction." (PMID 38534769, 2024). "Furthermore, we also examined the expression of several other key genes associated with immune regulation in different groups, including KLRB1, CD70, and FASLG, which have been shown to play key roles in glioma immune evasion." (PMID 38971948, 2024). "First, gliomas express FAS-Ligand that could induce FAS-L/FAS-mediated apoptosis of lymphocytes in the brain." (PMID 38168422, 2023). "Inhibition of the FASLG signaling pathway can prevent the invasion of glioma." (PMID 35855654, 2022). "To investigate whether CYB561D2-activated STAT3 induces the expression of immunosuppressive genes in gliomas, we measured protein expression of FASLG, TGF-β2, CD70, PD-L1, PD-L2, CCL2 and TDO2 in U251 and U87 transfected with CYB561D2 plasmid for 48 h." (PMID 34372858, 2021). "As shown by the bean plot, 7 genes (RIPK1, RIPK3, FAS, FADD, FASLG, TLR3, and TNF) were upregulated in the glioma tissues with p <0.001." (PMID 35719998, 2022). "Compared with NKTs cultured alone, the expression of antitumor molecules, including perforin, Fas ligand, and IFN-γ, was significantly reduced in NKTs co-cultured with glioma cells." (PMID 34603399, 2021). "Although BCL2 at low expression levels in gliomas is antiapoptotic, high levels of BCL2 facilitate FASLG-mediated apoptosis in this cancer type." (PMID 23777485, 2013). "The high expression of TLR3 in lower grade glioma (LGG) and LUSC; FASLG in LGG, UVM, KIRC, and THYM; RIPK3 in LGG, KIRC, and LUSC; RIPK1 in LGG and THCA; FAS in LGG, UVM, and THYM; MLKL in LGG, UVM, and LUAD; FADD in LGG and HNSC; and TNF in UVM and CESC was associated with poor survival." (PMID 35748782, 2022).
colon carcinoma (67 papers, 2001 to 2025). "The FASLG signaling pathway can be inhibited by the protein decoy receptor 3 (DcR3), which has been found to be elevated in lung and colon cancers." (PMID 36359256, 2022). "In a study, decreased expression of Fas, Fas ligand (FasL), and pro-caspase-8 were determined in colon cancer cells upon 5-FU treatment, suggesting the promotion of resistance through the extrinsic pathway." (PMID 34571731, 2021). "In colon carcinoma cells, ET-1 inhibits apoptosis mediated by Fas-ligand (FasL), which induces cell death via caspase activation, or Paclitaxel." (PMID 15226779, 2004). "Expression of membrane-bound Fas ligand (mFasL) on colon cancer cells serves as a potential mechanism to inhibit host immune function by inducing apoptosis of host lymphocytes." (PMID 11592778, 2001). "Moreover, lung and colon cancers exhibited enrichment of FASLG, but a greater degree of variability was observed between tumour types, with no increase noted in pancreatic or breast data sets examined." (PMID 29507342, 2018). "Previous research showed in tumor-infiltrating cytotoxic T lymphocytes (CTLs) in human colon carcinoma that SUV39H1 mediated H3K9me3 marks at the promoters of CTL effector genes (e.g., GZMB, PRF1, FASLG, and IFNG)." (PMID 40059829, 2025). "Vorinostat in combination with chemotherapeutic agent decitabine increased sensitivity of Fas ligand (FasL)-induced apoptosis and CTL immunotherapy via promotion of CD8+ T cells in colon cancer cells." (PMID 36969235, 2023). "As it occurred with TRAIL and Fas ligand, frequencies of GZMB+ cells changed after incubation with colon cancer cells." (PMID 34535957, 2021). "It has been reported that Cisplatin promotes Fas death receptor pathway apoptosis independent of Fas ligand in human colon cancer cells." (PMID 37365643, 2023). "Previous studies show that the BJOE combination therapy could promote liver cancer cell apoptosis by regulating the expression of soluble Fas/soluble Fas ligand and BJOE also induces apoptosis in the colon cancer cells." (PMID 29649989, 2018). "Ezrin phosphorylation on threonine 567, although reported as a prerequisite for Fas aggregation and caspase-8 activation, did not enhance Fas ligand- nor TRAIL-induced cell death in colon cancer cells." (PMID 26010871, 2015). "Apoptosis induced by CPDD, VP16 and vinblastine (VB) was shown involve Fas receptor clustering and Caspase 8 activation and was independent of Fas ligand in various colon cancer cells and leukaemia cells." (PMID 12402161, 2002). "SLE also triggered apoptosis in human cervical cancer HeLa cells through Fas/Fas ligand (FasL) expression promoted the activity of protein kinase A (PKA) in the gastric cancer cells and provoked caspase-3-mediated apoptosis in human colon cancer colo 205 cells." (PMID 22611426, 2012).
autoimmune lymphoproliferative syndrome (60 papers, 2007 to 2026). Autoimmune lymphoproliferative syndrome (ALPS) is a rare, inherited disorder characterized by non-malignant lymphoproliferation, multilineage cytopenias, and a lifelong increased risk of Hodgkin's and non-Hodgkin's lymphoma. "The main regulator of AICD is the Fas/Fas ligand (FasL) system, and mutations in Fas or FasL are the cause of the autoimmune lympho-proliferative syndromes (ALPS)." (PMID 30759880, 2019). "The importance of FAS and FAS ligand for immune regulation is obvious in patients with autoimmune lymphoproliferative syndrome (ALPS) due to mutations in the FAS and FASLG genes." (PMID 37187762, 2023). "Autoimmune lymphoproliferative syndrome (ALPS) is a group of disorders primarily due to impaired lymphocyte apoptosis, whose typical forms are caused by defects in the FAS pathway (FAS, FASLG, and CASP10)." (PMID 35601409, 2022). "As an example, autoimmune lymphoproliferative syndrome (ALPS) is characterized by defective Fas-mediated apoptosis in lymphocytes caused by genetically impaired regulation of Fas, Fas ligand and their effectors." (PMID 33198123, 2020). "Furthermore, patients with autoimmune lymphoproliferative syndrome (ALPS) have been shown to carry somatic or germline mutations in the genes that encode FAS, Fas-ligand, caspase 10, caspase 8, NRAS, and KRAS." (PMID 32121251, 2020). "Casp8−/−Ripk3−/− and Casp8−/−Mlkl−/− mice, characterized by splenomegaly with a marked accumulation of CD3+CD4−CD8−B220+ T cells, resemble the deficiency of FAS ligand (FasL, CD95L) or FAS (CD95) in mice or the autoimmune lymphoproliferative syndrome (ALPS) in humans." (PMID 35064213, 2022). "Disturbed apoptosis may be involved in SLE and other autoimmune/inflammatory conditions, and mutations in the FAS (Fas cell surface death receptor) or FASL (Fas ligand) genes, regulators of activation-induced cell death, result in autoimmune lymphoproliferative syndrome (ALPS)." (PMID 33569643, 2021).
viral infection (56 papers, 2007 to 2025). "CD8+ T cells control viral infections by triggering apoptosis of infected cells via perforin or Fas ligand-dependent pathways or producing antiviral cytokines (e.g., IFN-γ and TNF-α)." (PMID 40632810, 2025). "Particularly, CD8+ T cells are essential in protecting from WNV infection, and they control viral infections by triggering apoptosis of infected cells through perforin- or Fas ligand-dependent pathways or producing antiviral cytokines (e.g., IFN-γ and TNF-α)." (PMID 40632810, 2025). "In response to viral infection, the intense inflammatory response allowed the upregulation of FASLG expression in lung tissues." (PMID 38894720, 2024). "Viral infection can also induce the expression of death receptors on infected cells, which leads to NK cell-mediated cytolysis via the engagement of the Fas ligand (FasL) and tumor necrosis factor-related apoptosis-inducing ligand (TRAIL)." (PMID 39133756, 2024). "TEM (effector memory T cells) and TEMRA (CD45RA+ effector memory T cells) carry the greatest amounts of perforin and Fas ligand, with their numbers increasing after viral infection." (PMID 39610716, 2024). "The type-II transmembrane protein Fas ligand (FasL) appears throughout the eye to purge activated T cells and neutrophils when they enter the eye where there are viral infections or foreign grafts." (PMID 38206586, 2024). "We also found increased expression of other co-inhibitory molecules (BTLA, FASLG, FAS, and IDO1) that are associated with the regulation of T-cell exhaustion during chronic viral infection." (PMID 32731586, 2020). "Cytotoxic CD8+ T cells (CTL) can control viral infection by killing virus-infected cells through various effector molecules (Granzymes, TRAIL, Fas ligand)." (PMID 36311794, 2022). "In addition to direct infection, viral infection can also mediate “extrinsic” apoptotic cell death of uninfected cells through the induction of TNF-related apoptosis-inducing ligand (TRAIL) and Fas ligand (FasL) in monocyte-derived macrophages and lymphocytes." (PMID 36990977, 2023).